ACKR5 (atypical chemokine receptor 5)
Description:
Atypical chemokine receptor that regulates chemokine levels and localization through chemokine binding, independently of activating classical ligand-induced signaling pathways such as G protein activation and Ca(2+) mobilization. Instead, it mediates chemokine sequestration, transport, or internalization to control their availability. Acts as a scavenger for a broad range of chemokines from CXC, CC and XC chemokine ligand families including CXCL9, CXCL10, CXCL12, CXCL13, CXCL11, CXCL14, CCL1, CCL11, CCL19, CCL25, CCL28 and XCL1. Is the only atypical receptor for chemokines CXCL13 and CCL28. Has a strong constitutive association with beta-arrestins, which is essential for intracellular receptor trafficking and chemokine scavenging, and occurs independently of ligand binding. Cooperates with ACKR3 and ACKR4 in regulating serum levels of CXCL12 and CCL19, respectively. Acts as an important modulator of cellular immunity (By similarity).
Synonyms: ADMR; GPR182; hrhAMR; G10D; AM-R; 7TMR; AMR; L1-R; gamrh
Tractability: Small molecule: it belongs to a druggable protein family. Antibody: UniProt places it where antibodies can reach, with medium confidence; UniProt predicts a signal peptide or a membrane-spanning region; its Gene Ontology location is reachable by antibodies, with medium confidence.
Target class: Adrenomedullin receptor; Family A G protein-coupled receptor; Membrane receptor; Peptide receptor (family A GPCR); Short peptide receptor (family A GPCR)
Gene: Protein-coding gene on chromosome 12 (56,994,492 to 56,998,889, forward strand). Ensembl gene ENSG00000166856.
Subcellular location: Cell membrane; Endosome membrane
Gene Ontology:
Molecular function: C-C chemokine binding; C-X-C chemokine binding; protein binding; receptor decoy activity; G protein-coupled receptor activity; transmembrane signaling receptor activity
Biological process: negative regulation of chemokine-mediated signaling pathway; G protein-coupled receptor signaling pathway
Cellular component: endosome; endosome membrane; plasma membrane; membrane
Genetic constraint (gnomAD): Loss-of-function variants: 0 observed, 0.31 expected, observed/expected ratio (o/e) 0, 90% interval 0 to 1.86. That is too few expected variants to judge how well the gene tolerates losing a copy. Missense variants: 511 observed, 550.01 expected, observed/expected ratio (o/e) 0.93, 90% interval 0.86 to 1. Synonymous variants: 213 observed, 234.31 expected, observed/expected ratio (o/e) 0.91, 90% interval 0.81 to 1.02.
Homologues: Orthologues: chimpanzee GPR182 (99% identical), macaque GPR182 (93% identical), pig GPR182 (73% identical), rat Gpr182 (72% identical), guinea pig GPR182 (72% identical), mouse Gpr182 (72% identical), rabbit GPR182 (70% identical), dog GPR182 (66% identical), tropical clawed frog gpr182 (51% identical), zebrafish gpr182 (33% identical). Paralogues in human: GPER1 (24% identical).
Diseases named in the same sentence as ACKR5 in open-access papers:
ACKR5 is named in the same sentence as 25 diseases in open-access papers, as found by Europe PMC text mining. Sharing a sentence is not in itself a finding about the gene and the disease.
ACKR5 shares sentences with these, for which no sentence is quoted: tumor (12 papers); cancer (5); infection (4); pancreatic cancer (2); adenoma (1); autism (1); bacterial infection (1); breast carcinoma (1); colorectal cancer (1); COVID-19 (1); Familial adenomatous polyposis (1); hepatocellular carcinoma (1); infectious disease (1); Klebsiella Infections (1); liver cancer (1); liver fibrosis (1); melanoma (1); metastatic melanoma (1); myeloid leukemia (1); Obesity (1); periodontitis (1); pulmonary hypertension (1); smallpox (1); Stroke (1); tuberculosis (1).